LAMA1 (laminin subunit alpha 1)
Diseases named in the same sentence as LAMA1 in open-access papers (continued):
Sharing a sentence is not in itself a finding about the gene and the disease.
Retinal dystrophy (3 papers, 2018 to 2025). Retinal dystrophy is an abnormality of the retina associated with a hereditary process. "However, as with other ocular phenotypes, there was no clear association between specific LAMA1 variants and the presence or severity of retinal dystrophy." (PMID 40428839, 2025).
Alzheimer disease (2 papers, 2020 to 2023). A progressive, neurodegenerative disease characterized by loss of function and death of nerve cells in several areas of the brain leading to loss of cognitive function such as memory and language. "In a study on degenerative diseases, D'Aoust and colleagues were the first to discover that LAMA1 rs73938538 A > C was positively related to Alzheimer's disease in the Amish community." (PMID 36824663, 2023).
autism (2 papers, 2013 to 2021). Persistent deficits in social interaction and communication and interaction as well as a markedly restricted repertoire of activity and interest as well as repetitive patterns of behavior. "Moreover, the candidate genes PAK3, OCRL, DCX, PTK2, KCNQ3, SOX3, and LAMA1 were associated with autism, brain disease, Dent disease, and other conditions that present ID as a hallmark, corroborating our findings." (PMID 33922640, 2021).
colon cancer (2 papers, 2019 to 2023). "Recent research indicates that LAMA1 mutations or overexpression are linked with the occurrence and development of various malignant tumors, including colon cancer, pancreatic cancer, and ovarian cancer." (PMID 36824663, 2023).
congenital muscular dystrophy (2 papers, 2018 to 2022). A muscular dystrophy that is characterized by diminished muscle tone (hypotonia), progressive muscle weakness and degeneration (atrophy), abnormally fixed joints, spinal rigidity, and delays in reaching motor milestones such as sitting or standing unassisted. "Upregulation of Lama1 in muscle was shown to prevent muscle fibrosis and weakness in the murine model dy2j/dy2j of laminin α2 deficient congenital muscular dystrophy." (PMID 36041985, 2022).
congenital myasthenic syndrome (2 papers, 2020 to 2022). Congenital myasthenic syndrome (CMS) is a group of genetic disorders of impaired neuromuscular transmission at the motor endplate characterized by fatigable muscle weakness. "One pair of homozygous variants in LAMA5 (p.Arg2659Trp) and one homozygous variant in LAMA1 were identified in a patient with the presynaptic congenital myasthenic syndrome who has non-classified facial tics or tics." (PMID 35663266, 2022).
diabetes (2 papers, 2012 to 2024). "Previous cell biology studies support a role for LAMA1, encoding laminin-1, in diabetes etiology - inhibition of LAMA1 expression reduced glucose-stimulated secretion in INS1E cells." (PMID 22693455, 2012).
gastric cancer (2 papers, 2021). A primary or metastatic malignant neoplasm involving the stomach. "GLI3, LAMA1, and LRRK2 are found to be significantly associated with the survival of gastric cancer in subtype C1." (PMID 34728653, 2021).
glioma (2 papers, 2015 to 2022). A benign or malignant brain and spinal cord tumor that arises from glial cells (astrocytes, oligodendrocytes, ependymal cells). "DUSP4 expression in glioma correlates with the GFAPδ/α ratio, and high expression is associated with a worse prognosis.LAMA1 associated with gliomas invasion was increased in cells with a high GFAPδ expression compared to GFAPα." (PMID 35372061, 2022). "Several genes including e.g. F5, LAMA1, ERBB2 or STARD3 seems to be in proximity to genes of the EGF/EGFR signaling cascade, which is known to be important in glioma." (PMID 25537509, 2015).
Joubert syndrome (2 papers, 2021 to 2024). Joubert syndrome (JS) is characterized by congenital malformation of the brainstem and agenesis or hypoplasia of the cerebellar vermis leading to an abnormal respiratory pattern, nystagmus, hypotonia, ataxia, and delay in achieving motor milestones. "Similarly, among ∼14,000 individuals with developmental disorders recruited in the UK deciphering developmental disorders study, 26 (∼0.2%) were solved for a Joubert syndrome gene and three cases solved with LAMA1 variants." (PMID 34423300, 2021). "In our study, we identified two cases, MOL2246-1 and MOL22151-1, marking the first documented instances in Israel of Joubert syndrome associated with mutations in the ARMC9 and LAMA1 genes, respectively." (PMID 39062705, 2024). "On the other hand, the relative contribution of LAMA1 to developmental disorders is likely comparable to the more common among the Joubert syndrome genes, when considered individually." (PMID 34423300, 2021). "We have shown here that there is a certain phenotypic overlap, especially in infancy, between Joubert syndrome and PTBHS, and therefore it seems a pragmatic approach to add the single LAMA1 gene to Joubert syndrome gene panels so this alternate diagnosis can be detected." (PMID 34423300, 2021). "We conclude that children with congenital brain disorders that mimic Joubert syndrome may have a delayed diagnosis due to poor recognition of key features on brain imaging and the lack of inclusion of LAMA1 on molecular genetic gene panels." (PMID 34423300, 2021).
ovarian carcinoma (2 papers, 2022 to 2023). A malignant neoplasm originating from the surface ovarian epithelium. "A recent study showed that LAMA1, a subunit of laminin, was associated with poor prognosis and was negatively correlated with CD8+ T cell infiltration in ovarian cancer." (PMID 35389889, 2022).
retinal diseases (2 papers, 2011 to 2016). "The present study strongly suggests that mutations in LAMA1 or other ILM components in humans could cause retinal diseases such as PFV, PVR, and retinal detachment." (PMID 21999428, 2011).
alopecia areata (1 paper, 2021). Loss of scalp and body hair involving microscopically inflammatory patchy areas. "For the three patients with LAMA1 mutations, alopecia areata appeared in the midline of the parietal region (in the center of hair whorl)." (PMID 34249907, 2021). "Further function study is needed to clarify the pathogenesis between LAMA1 mutation and alopecia areata in the occipital region or parietal region of the cranial midline." (PMID 34249907, 2021). "In the present study, pathogenic mutations were detected in six early onset high myopia patients with midline alopecia areata, and the causative genes included not only the COL18A1 gene but also the LAMA1 gene." (PMID 34249907, 2021).
amoebiasis (1 paper, 2024). "Within the biological process of amoebiasis, dietary supplementation with PPAH decreased the expression of several genes, including Il6, Serpinb9c, Rab5a, Muc2, Rab7, Lamb1, and Lama1." (PMID 39591294, 2024).
breast tumors (1 paper, 2024). "In metastatic human breast tumors, overexpression of fibronectin and LAMA1 proteins were exhibited in mice, promoting the degradation processes of extracellular matrix proteins in cancer metastasis." (PMID 38951817, 2024).
clear cell renal cell carcinoma (1 paper, 2022). "In clear cell renal cell carcinoma, LAMA1 is one of the markers associated with early metastatic cancer." (PMID 35070505, 2022).
cutaneous melanoma (1 paper, 2020). A primary melanoma arising from atypical melanocytes in the skin. "Here, LAMA1 and LAMB1 have been identified as potential markers for cutaneous melanoma metastasis as these proteins are involved in the modulation of cell adhesion and migration." (PMID 32886718, 2020).
diabetic nephropathy (1 paper, 2018). "As in vitro and in vivo studies indicate that LAMA1 deficiency promotes mesangial cell proliferation and that this pathological change is very similar to diabetic nephropathy, we hypothesize that hyperglycemia can influence the proliferation of retinal endothelial cells through the LAMA1-TGF-β axis." (PMID 29967796, 2018).
esophageal squamous cell carcinoma (1 paper, 2023). Esophageal squamous cell carcinoma (ESCC) is a type of esophageal carcinoma (EC) that can affect any part of the esophagus, but is usually located in the upper or middle third. "We analyzed the association of several genetic models of 6 LAMA1 SNP loci, sex, age, smoking and drinking status, and the occurrence of esophageal squamous cell carcinoma." (PMID 36824663, 2023). "Through our multicenter large-samplecase-control study, we found that rs62081531 locus G > A and rs607230 locus T > C of LAMA1 were independent protective factors for esophageal squamous cell carcinoma, especially in those younger than 65 and nondrinkers." (PMID 36824663, 2023).
glioblastoma (1 paper, 2026). The most malignant astrocytic tumor (WHO grade IV). "LAMA1 (Laminin α1) gene was high expression in primary glioblastoma in contrast to normal brain tissue, and the over-expression of LAMA1 was associated with aggressive phenotypes in ESCC, while the high expression of LAMA1 patients had a shorter PFS or OS than low expression patients." (PMID 41438689, 2026).
Knobloch syndrome (1 paper, 2021). "Further assessments indicated that patients with COL18A1 mutations had Knobloch syndrome, and the patients with LAMA1 mutations had Poretti–Boltshauser syndrome." (PMID 34249907, 2021).
malaria (1 paper, 2022). Malaria is a serious and sometimes fatal disease caused by a parasite that commonly infects a certain type of mosquito which feeds on humans. "The response of Lamb1 expression to malaria differed from that of Lama1, though there was an almost similar unresponsive phase in unvaccinated mice until day 4 p.i., as also observed for Lama1." (PMID 35214745, 2022).
muscular dystrophy (1 paper, 2021). Muscular dystrophy (MD) refers to a group of more than 30 genetic diseases characterized by progressive weakness and degeneration of the skeletal muscles that control movement. "Potential therapeutic interventions including splice modulation, upregulation of the LAMA1 gene, mini-agrin and αLNNd are in development for LAMA2-related muscular dystrophy." (PMID 34281576, 2021).
myocardial infarction (1 paper, 2024). Gross necrosis of the myocardium, as a result of interruption of the blood supply to the area, as in coronary thrombosis. "LAMA1, LAMA3 and LAMA5, other laminins, are targets of the approved drug lanoteplase, used in the treatment of myocardial infarction but with unknown mechanisms of action." (PMID 38383672, 2024).
neovascular glaucoma (1 paper, 2025). "The unrelated child with a LAMA1 deletion spanning exons 17-23 presented with abnormal development of retinal vasculature that was complicated with vitreous hemorrhage and neovascular glaucoma." (PMID 39925523, 2025).
pancreatic cancer (1 paper, 2014). "Our results add further support to the hypothesis that inherited duplications at the LAMA1 locus may be involved in pancreatic cancer risk." (PMID 24592275, 2014).
proliferative vitreoretinopathy (1 paper, 2011). Vitreoretinal membrane shrinkage or contraction secondary to the proliferation of primarily retinal pigment epithelial cells and glial cells, particularly fibrous astrocytes, followed by membrane formation. "The membranes formed by astrocytes in Lama1 mutants also resemble epiretinal membranes seen in patients with proliferative vitreoretinopathy (PVR), a complication of retinal detachment in which retinal cells and macrophages enter the vitreous." (PMID 21999428, 2011). "The Lama1 mutants described in this report are potential models for studying the human conditions persistent fetal vasculature and proliferative vitreoretinopathy." (PMID 21999428, 2011).
pulmonary fibrosis (1 paper, 2023). Chronic progressive interstitial lung disorder characterized by the replacement of the lung tissue by connective tissue, leading to progressive dyspnea, respiratory failure, or right heart failure. "Based on haplotype-based computational genetic mapping and mRNA profiling, Laminin α1 (Lama1) was chosen for analysis among other candidates due to its high genetic effect on TGF-β1-induced pulmonary fibrosis." (PMID 37681924, 2023). "Lama1 aggravates pulmonary fibrosis, as revealed by collagen deposition and collagen-related gene expression." (PMID 37681924, 2023).
tubulinopathy (1 paper, 2023). A nervous system disorder characterized by complex cortical malformations including in most cases dysmorphic basal ganglia and/or corpus callosum in which the cause of the disease is a variation in a tubulin gene. "The clinical diagnoses of PTBHS and tubulinopathy were confirmed by detection of causative variants in LAMA1 and TUBA1A, respectively." (PMID 37131188, 2023).
Ventriculomegaly (1 paper, 2020). An increase in size of the ventricular system of the brain. "In a family with two consecutive pregnancies affected with ventriculomegaly, a splicing likely pathogenic variant at the LAMA1 locus (NM_005559: c." (PMID 33083009, 2020).
cancer (31 papers, 2012 to 2025). A tumor composed of atypical neoplastic, often pleomorphic cells that invade other tissues. "The expression levels are very similar between sample groups and only the PKHD1 and LAMA1 genes have been implicated, so far, in cancer." (PMID 29844869, 2018). "Evaluation of the KEGG dataset showed enrichment through laminins (LAMA1, LAMA5, LAMB1, LAMB2, LAMC1, LAMC3) that are associated with ECM–receptor interactions, focal adhesion, and pathways in cancer." (PMID 41614767, 2025). "In comparison to normal tissues, Nos2, Hgf, Lama1, Csf3r, Csf2rb2, Col4a1, Col4a2, Adcy2, Adcy4, Gstm3 and Gstm6 were identified as the most significant genes in cancer pathways." (PMID 37774039, 2023). "For laminin subunit alpha 1, there were 6 positive correlations with 6 cancer types and inverse correlations with 5 cancer types." (PMID 36230521, 2022). "In addition, we analyzed the correlation pair-wise (Pearson’s correlation test), between PEBP1 (RKIP) and SNAI1, VIM, CDH1/2, EPCAM, and LAMA1/B1 genes, across the 22 different types of cancer and normal tissues in the TCGA database." (PMID 36230521, 2022). "A particularly interesting potential interaction with high relevance for tumor biology includes JAG2 (cancer) with NOTCH3 (mouse stroma), and interactions of integrins (ITGA2, ITGA2B) with ECM proteins (COL2A1, LAMA1)." (PMID 35053442, 2022). "Among the listed ECM genes, two types were noted, those that were low in mono-cultures and high in co-cultures (e.g. COL1A, FN, LAMA1, primarily fibroblast-derived) and those that were high in both mono- and co-cultures (e.g. LAMA5 and LAMB1, primarily cancer cell-derived)." (PMID 39011470, 2024). "In addition, this panel includes ECM components that stimulate cancer cell invasion, such as collagens (e.g., COL1A1, COL4A1), the extracellular matrix glycoproteins laminins (e.g., LAMA1, LAMC1), fibronectin (FN1), and SPARC, among others." (PMID 38437557, 2024). "This suggested that, as individual genes, INHBB, LAMA1, SCGB3A1 and OPG can indeed promote metastatic colonization, and that coexpression of the four genes may provide a further advantage to cancer cells." (PMID 35469015, 2022). "LAMA1, CHAD, ITGA8, and COL11A1 consistently showed hypermethylation in more than half of cancer types; on the contrary, TNN, SPP1, COL6A6, and TNR consistently showed hypomethylation in more than half of types of cancer." (PMID 36311789, 2022). "LAMB3, along with LAMA1, LAMA3 and LAMC2, was enriched in pathways involved in cancer." (PMID 28904855, 2017). "Similarly, testis-restricted targets such as SPA17, TEX14, LAMA1, SMOC1, TNFAIP6, GPC2, and COL20A1 may also be leveraged for their cancer-specificity." (PMID 38702309, 2024).
tumor (27 papers, 2013 to 2025). "In addition, suppression of LAMA1 partly abolished the promotional effect on tumor growth caused by circPDE3B overexpression." (PMID 34226522, 2021). "Intriguingly, immunofluorescence analysis of Laminin distribution in the dECM-tumor tissues revealed a reduction in LAMA1 abundance specifically within regions populated by the tumor nodes." (PMID 40166338, 2025). "The in vivo tumor formation assay suggested that LAMA1 knockdown conspicuously inhibited tumor growth, while circPDE3B overexpression greatly promoted it when compared to the NC." (PMID 34226522, 2021). "FN1, ITGA5, THBS2, and LAMA1 were associated with cell adhesion and metastasis, and the expression of TGFB1, COL4A1, COL4A2, and THBS2 inhibited tumor growth." (PMID 34370778, 2021). "When we looked at all SNV, we discovered previously undescribed mutations shared between tumor-organoid pairs, such as AHNAK2 and LAMA1 (shared between EDO 74 and 82) and LILBR2 (shared between EDO 92 and 74)." (PMID 32884042, 2020). "LAMA1 and AHNAK has been implicated in tumor metastasis while TSC2 is considered tumor suppressor." (PMID 36026497, 2022). "Interestingly, LAMA1 downregulation greatly decreased metastatic tumor number and size, and the enforced circPDE3B expression again counteracted this change." (PMID 34226522, 2021). "Among the downregulated DEGs, four genes (LAMA1, ASPRV1, IL1B, PRR4) displayed reduced expression, while two genes (CCDC157, RP1) showcased elevated expression in tumor compared to normal tissue, respectively." (PMID 39062832, 2024). "Of the 11 neoplasm-related genes in these subclusters, the expression of six (ANGPT2, TP73, NOVA1, CDH11, CXCL12, and LAMA1) were significantly repressed in KRT and one (EPHA2) was higher expressed in KRT compared with IMU." (PMID 37654626, 2023). "LAMA1/A5 and LAMC1 were significantly and negatively correlated with various tumor immune infiltrates (TILs), especially with dendritic cells, CD8+ T cells or neutrophil." (PMID 34512203, 2021). "Components of ECM (LAMA1, 3, and 5) induce the synthesis of PA by activation of PLD which stimulates matrix metalloproteinases (MMPs) and enhances the invasive capacity of tumor cells." (PMID 29062084, 2017). "Regardless of tumor or other nontumor diseases, LAMA1 is essential for vascular homeostasis and the basal layer of blood vessels." (PMID 36824663, 2023). "Moreover, LAMA1/A5 and LAMC1 were significant negatively correlated with tumor immune infiltrates in OV, especially with dendritic cells, CD8+ T cells or neutrophil." (PMID 35612641, 2022). "Moreover, the mutations ALPK2.R136S, CHST9.S122N, FAM38B.V2463, LAMA1.S1577A, LAMA1.K2002E, MYOM1.T215M, SERPINB10.R246C and SLC14A2.A880T were found in all three tumor samples and shared a similar frequency profile." (PMID 23892400, 2013). "Of note, the main source of LAMA1 (Laminin Subunit Alpha 1) signal detected was from the dECM scaffold and thus it was present throughout the scaffold, in regions both with and without the presence of tumor cells (DAPI)." (PMID 40913457, 2025). "However, LAMA1 was not statistically significantly different between groups, while LAMC3 and LAMB4 showed slight decreases in expression in tumour samples." (PMID 37779898, 2023).
genetic disease (2 papers, 2025). "PBS is a rare genetic disorder associated with LAMA1 variants, leading to a broad spectrum of systemic and ocular manifestations." (PMID 40428839, 2025).
infection (2 papers, 2012 to 2025). The state of being infected such as from the introduction of a foreign agent such as serum, vaccine, antigenic substance or organism. "Clade I infection was associated with 15 enriched GO terms, driven in part by up-regulation of LAMA1 and LAMA2 (orthologues of Laminin subunit-α)." (PMID 41419766, 2025). "Furthermore, LAMA1 (Laminin, alpha 1) interacts with Fibulin-2 (FBLN2), an ECM protein that binds various extracellular ligands and calcium and appears to be involved in the infection process." (PMID 23133440, 2012).